EZH2 (enhancer of zeste 2 polycomb repressive complex 2 subunit)
Diseases named in the same sentence as EZH2 in open-access papers (continued):
Sharing a sentence is not in itself a finding about the gene and the disease.
osteosarcoma (continued). "Knockdown of EZH2 expression in osteosarcoma cells resulted in slower migration and repressed invasion activity." (PMID 27223261, 2016). "In order to further investigate the function of EZH2 in osteosarcoma, we mimicked the in vivo environment by using a three-dimensional cell culture." (PMID 27223261, 2016). "To investigate the level of EZH2 expression in osteosarcoma, we detected its protein levels in a series of osteosarcoma cell lines and clinical specimens." (PMID 27223261, 2016). "In the present study, we found that EZH2 was constitutively highly expressed in osteosarcoma cell lines and tissues." (PMID 27223261, 2016). "The data showed that pharmacologic disruption of EZH2 via DZNep inhibited growth in osteosarcoma cell lines in a dose-dependent manner." (PMID 27223261, 2016). "Our study observed that knockdown of EZH2 significantly inhibited osteosarcoma cell growth, survival, and clonogenicity, as well as decreased cell migration and invasion ability, implying that EZH2 plays an important role in osteosarcoma progression." (PMID 27223261, 2016). "To investigate the clinical relevance between EZH2 expression and osteosarcoma clinical behavior, we evaluated the clinicopathologic features of the osteosarcoma tumor samples." (PMID 27223261, 2016). "Altogether, these results suggest that knockdown of EZH2 increases the sensitivity of osteosarcoma cells to chemotherapeutic agents." (PMID 26265454, 2015). "The results indicated that EZH2 expression was highly expressed, suggesting its oncogenic role in osteosarcoma." (PMID 26265454, 2015). "Herein, we show that EZH2 silencing inhibits tumor growth and lung metastasis in osteosarcoma by facilitating re-expression of the imprinting gene tumor-suppressing STF cDNA 3 (TSSC3)." (PMID 26265454, 2015). "EZH2 knockdown considerably inhibited lung metastasis of osteosarcoma cells, as reflected by the incidence, number, size and weight of the metastatic nodules." (PMID 26265454, 2015). "This is the first study that identifies the role of EZH2 in the growth and metastasis of osteosarcoma in vivo and its relationship with TSSC3." (PMID 26265454, 2015). "Silencing of EZH2 increased apoptosis in osteosarcoma cells treated with cisplatin, indicated by TUNEL assay and annexin V/7-AAD analysis." (PMID 26265454, 2015). "The results showed that the expression of EZH2 appeared to be much higher in the cell lines derived from high-grade osteosarcoma (MTF, U2OS and SaOS2), meanwhile it was much lower in cell lines derived from low-grade osteosarcoma (MG63 and HOS)." (PMID 26265454, 2015). "We have demonstrated that EZH2 plays a crucial role in tumor growth and distant metastasis in osteosarcoma; its oncogenic role is related to its regulation of the expression of TSSC3." (PMID 26265454, 2015). "Initial investigations in osteosarcoma cells indicated that EZH2 suppresses TSSC3 expression both at the transcript and protein levels, through histone H3K27 trimethylation at the TSSC3 promoter." (PMID 26265454, 2015). "Our results suggest that knockdown of EZH2 made osteosarcoma cells more sensitive to the cytotoxic effects of cisplatin." (PMID 26265454, 2015). "In the present study, using two human osteosarcoma cell lines, inhibition of EZH2 expression led to cell cycle arrest in G1 phase, reduced cell growth/proliferation in vitro and in vivo." (PMID 26265454, 2015). "Further studies to investigate the exact mechanism by which EZH2 regulates the apoptotic pathway in osteosarcoma needs further examination." (PMID 26265454, 2015). "In the present study, we demonstrate the role for EZH2 in osteosarcoma from the aspect of TSSC3′s epigenetic regulation." (PMID 26265454, 2015). "In summary, a positive relationship was found between EZH2 and tumor growth and metastasis of osteosarcoma." (PMID 26265454, 2015).
osteosarcoma (continued). "The EZH2 positive expression rate in osteosarcoma was 48.75%, notably higher than the osteoblasts in osteoblastoma, which is from the benign lesions in bone (P < 0.01)." (PMID 26265454, 2015). "PRAME promotes the proliferation of osteosarcoma cells, while in Chronic myelogenous leukemia, in the presence of RA and PcG proteins, including EZH2, it binds to retinoic acid receptor (RAR) to block Caspase 3, TRAIL, and P21 expression, leading to proliferation and apoptosis arrest." (PMID 40961095, 2025). "Blocking EZH2 activity results in a reduction of osteosarcoma lung metastases." (PMID 38886296, 2024). "While EZH2-overexpression is associated with prevalence of osteosarcoma, EZH2-knockdown did not prevent osteosarcoma progression." (PMID 40135141, 2024). "Moreover, lncRNA HOXD-AS1 recruits EZH2 to the p57 promoter, epigenetically silences p57 expression, and promotes osteosarcoma growth." (PMID 37345170, 2023). "Several studies have documented the involvement of EZH2 with lncRNAs in osteosarcoma." (PMID 35755302, 2022). "EZH2 is identified to promote the progression of osteosarcoma through activating AKT." (PMID 36712870, 2022). "Furthermore, we analyzed the relationship between FBP1 and EZH2 in OC based on TCGA cohorts, and we confirmed a positive correlation between FBP1 and EZH2 in osteosarcoma cells." (PMID 36000567, 2022). "The present investigation hypothesized that circular RNA_ANKIB1 accelerates osteosarcoma chemo-resistance via binding microRNA-26b-5p and modulating EZH2." (PMID 35264070, 2022). "In addition, higher protein expression of EZH2 was detected in osteosarcoma patients where it significantly correlated with shorter disease free and overall survival." (PMID 34198693, 2021). "FOXD2-AS1/EZH2 silences p21 transcription, and thus apoptosis in hypoxia-induced osteosarcoma." (PMID 33050646, 2020). "To further investigate the clinical relevance between EZH2 expression and osteosarcoma behavior, we also analyzed the relationship between EZH2 mRNA expression and the survival of osteosarcoma patients from 53 osteosarcoma tumor samples in a microarray dataset (GSE21257)." (PMID 27223261, 2016). "Different levels of EZH2 expression were observed in these osteosarcoma patient samples." (PMID 27223261, 2016). "Overexpression of EZH2 has been found in several malignancies, however, its expression and the role of EZH2 in osteosarcoma is largely unknown." (PMID 27223261, 2016). "Moreover, RNAi mediated EZH2 knockout induced growth inhibition in a time-dependent manner in both osteosarcoma cell lines U2OS and SAOS." (PMID 27223261, 2016). "EZH2 silencing by siRNA inhibited osteosarcoma cell growth, proliferation, migration, and invasion." (PMID 27223261, 2016). "Consistent with the findings of EZH2 siRNA silencing in osteosarcoma cells in this study, treatment of osteosarcoma cell lines U2OS and SAOS with DZNep resulted in significant reduction of EZH2 protein levels and subsequently decrease H3K27me3 levels in a dose-dependent manner." (PMID 27223261, 2016). "Furthermore, patients with osteosarcoma presenting with high EZH2 expression exhibited a worse prognosis than those with low EZH2 expression." (PMID 27223261, 2016). "EZH2 expression was also analyzed in a microarray dataset of osteosarcoma." (PMID 27223261, 2016). "Notably, the mRNA expression level of EZH2 was significantly up-regulated in osteosarcoma patients who developed metastases within five years than in patients who did not develop metastases within five years (P = 0.0314)." (PMID 27223261, 2016). "Furthermore, we confirmed for the first time that DZNep is effective in reducing EZH2 expression and inhibits tumor growth in osteosarcoma." (PMID 27223261, 2016). "Furthermore, stem cell markers of CD44 and Notch-3 were decreased in osteosarcoma cells after inhibition of EZH2." (PMID 27223261, 2016).
osteosarcoma (continued). "Furthermore, Kaplan-Meier survival analysis revealed that patients with high EZH2 expression had shorter survival in this cohort of osteosarcoma patients (P = 0.0310)." (PMID 27223261, 2016). "To determine whether TSSC3 is involved in EZH2’s regulation of osteosarcoma cell proliferation, metastasis and apoptosis, we performed rescue experiments." (PMID 26265454, 2015). "In the present study, we examined the expression of EZH2 in osteosarcoma samples by IHC." (PMID 26265454, 2015). "The wound healing results suggested that the silencing of EZH2 could severely inhibit migration of osteosarcoma cells." (PMID 26265454, 2015). "Lenti-shEZH2 was employed to effectively knockdown the expression of EZH2 in osteosarcoma cells." (PMID 26265454, 2015). "In addition, we performed rescue experiments to determine whether EZH2 is involved in the lincFOXF1‐induced decrease in osteosarcoma cell metastasis." (PMID 32945076, 2020). "Measuring EZH2 expression level may carry potential as a novel molecular biomarker of osteosarcoma." (PMID 27223261, 2016). "Further correlation analyses revealed that abnormally high expression of EZH2 was positively correlated with increased aggressive and metastatic behavior, indicating that EZH2 expression may contribute to the progression of osteosarcoma by functioning as an oncogene." (PMID 27223261, 2016). "Finally, we further assessed the effects of DZNep on EZH2 protein expression in osteosarcoma cells." (PMID 27223261, 2016). "Furthermore, enhancing EZH2 expression reduced the inhibitory effects of miR-138 on osteosarcoma." (PMID 27019355, 2016). "EZH2 inhibitor DZNep can inhibit the growth of osteosarcoma cell lines, indicating that pharmacologically targeting EZH2 via an inhibitor may constitute a novel approach to the treatment of osteosarcoma." (PMID 27223261, 2016). "Thus, monitoring the expression level of EZH2 protein in osteosarcoma specimens may provide additional prognostic information, which is not discernible with current clinical and pathology parameters alone." (PMID 27223261, 2016). "Thus, the PI3K/AKT pathway may be involved in EZH2′s ability to promote tumor progression and metastasis in osteosarcoma." (PMID 26265454, 2015). "Furthermore, EZH2 was highly expressed in samples with lung metastasis (100% over 38.81%), suggesting EZH2 might be involved in the distant metastasis process of osteosarcoma." (PMID 26265454, 2015). "However, the downstream molecular events involving EZH2 and osteosarcoma growth and/or metastasis molecular mechanisms remain unclear." (PMID 26265454, 2015). "The upregulation of EZH2 epigenetically silences its target tumor suppressor gene PTEN and promotes osteosarcoma cell proliferation, growth, migration, and invasion." (PMID 37345170, 2023). "Namely, inhibition of the EZH2 in 143B and HOS osteosarcoma cells decreased H3K27me3 levels and led to cisplatin resistance." (PMID 36230683, 2022). "Overexpression of FOXP4-AS1 was found to regulate osteosarcoma progression by downregulating LATS1 (large tumor suppressor 1) through binding LSD1 (lysine-specific demethylase 1) and EZH2." (PMID 35755302, 2022). "Functionally, circ-LRP6 binds to both LSD1 and EZH2 and inhibits APC and KLF2 expression thereby promoting osteosarcoma progression." (PMID 35755302, 2022). "A study has displayed that FOXP4-AS1 binds to enhancer of zeste homolog 2 (EZH2) and then is involved in the progression of osteosarcoma." (PMID 34545456, 2022). "In osteosarcoma cells, we demonstrated that FBP1 physically binds with EZH2 and that a positive mutual regulatory mechanism exists between FBP1 and EZH2." (PMID 36000567, 2022). "In hypoxia-induced osteosarcoma, lncRNA FOXD2-AS1, upregulated by HIF1-α, binds to EZH2 and relocates to the promotor region of p21." (PMID 33050646, 2020). "In recent years, upregulation of EZH2 expression was also discovered in certain sarcomas, including Ewing sarcoma, RMS, synovial sarcoma, osteosarcoma and chondrosarcoma." (PMID 30120321, 2018).
osteosarcoma (continued). "The expression of miR-144-3p was reported to be low in osteosarcoma and lncRNA TUG1 targeting miR-144-3p promoted tumorigenesis through upregulating EZH2 expression." (PMID 30540564, 2018). "Moreover, Enhancer of zeste homolog 2 (EZH2) was found to be involved in loss of TSSC3 expression and the expression of TSSC3 could be altered by 5-Aza-CdR (a DNA methyltransferase inhibitor) treatment in osteosarcoma cells." (PMID 30092789, 2018). "We therefore examined the effect of EZH2 silencing on the protein expressions of cancer stem cell markers; include CD44 and Notch-3 in osteosarcoma cells." (PMID 27223261, 2016). "Therefore, EZH2 is a molecule that is involved in cancer cells migration and/or invasion and thus, the abnormal expression of EZH2 may provide a selective advantage in osteosarcoma cells invasiveness and/or metastasis." (PMID 26265454, 2015). "However, contrary to this, in an earlier study, it was shown that miR-138 targets EZH2 and elevates cisplatin-induced apoptosis in MG-63 and U2OS osteosarcoma cells." (PMID 36230683, 2022). "To this end, we first examined the extent of EZH2 expression in osteosarcoma cell lines and tumor samples in a 64 osteosarcoma patient cohort via tissue microarray (TMA) technology, and then analyzed the relationship between EZH2 expression and clinical behavior of osteosarcoma." (PMID 27223261, 2016). "In the subgroup analysis, the mean EZH2 expression for the non-survival group was significantly higher than the survival group for osteosarcoma (P = 0.00143)." (PMID 27223261, 2016). "EZH2 has been recognised as an oncogene in several types of tumors; however, its role in osteosarcoma has not been fully elucidated." (PMID 26265454, 2015). "Positive expression of EZH2 was frequently observed in high-grade osteosarcoma (52.7%), but not in low-grade osteosarcoma (0%)." (PMID 26265454, 2015). "Both in HDF and in easy-to-transfect human osteosarcoma (U2-OS) cells, overexpression of Ezh2 mRNA was transient and no elevation of Ezh2 protein levels was observed in HDF, for reasons that remain to be established." (PMID 23557329, 2013). "However, the expression status and functional role of EZH2 in tumorigenesis and progression of osteosarcoma has not yet been fully investigated." (PMID 27223261, 2016). "Second, while we showed that miR-138/EZH2 modulated osteosarcoma cell response to cisplatin, we did not specifically assess whether the enhanced chemosensitivity is mainly attributed to miR-138/EZH2, as miR-138 may target other genes as well." (PMID 27019355, 2016). "The association between EZH2 and TSSC3 expression has not been investigated in osteosarcoma." (PMID 26265454, 2015). "Moreover, 100% of stage III osteosarcoma patients showed positive expression of EZH2, whereas no positive result was detected in stage I tumors." (PMID 26265454, 2015).
Weaver syndrome (59 papers, 2011 to 2025). "The novel EZH2 variant c.449T>C (p.Ile150Thr) expands the molecular and phenotypic spectrum of Weaver syndrome." (PMID 41300605, 2025). "Based on the combination of the characteristic clinical phenotype and the identification of a pathogenic de novo EZH2 variant, the patient was definitively diagnosed with Weaver syndrome." (PMID 40922349, 2025). "We report a novel de novo EZH2 variant, c.449T>C (p.Ile150Thr), in a 4-year-old Taiwanese female with Weaver syndrome." (PMID 41300605, 2025). "Recently, a mouse model for the most common Weaver syndrome missense variant, EZH2 p.R684C was developed, and mouse embryonic fibroblasts (MEFs) obtained from these animals showed global depletion of H3K27me3." (PMID 40469903, 2025). "Recent functional studies indicate that pathogenic EZH2 variants in Weaver syndrome result in partial loss of histone methyltransferase activity, rather than complete haploinsufficiency." (PMID 41300605, 2025). "Weaver syndrome (WS) is caused by mutations in EZH2 (Enhancer of Zeste homolog 2) and is characterized by pre- and/or postnatal overgrowth, macrocephaly, advanced bone age, distinctive craniofacial features, and a variable degree of intellectual disability." (PMID 38448973, 2024). "EZH2 is a transcriptional repressor, mutations of which cause Weaver syndrome, a rare genetic disorder characterized by intellectual disability." (PMID 39299805, 2024). "Weaver syndrome is a Mendelian disorder of the epigenetic machinery (MDEM) caused by germline pathogenic variants in EZH2, which encodes the predominant H3K27 methyltransferase and key enzymatic component of Polycomb repressive complex 2 (PRC2)." (PMID 38015625, 2024). "Pathogenic variants in these genes can also result in overgrowth due to loss of PRC2 functionality similar to EZH2 in Weaver syndrome." (PMID 38894719, 2024). "Using the Weaver syndrome DNA methylation signature, we classified the DNA methylation profiles of a father–child pair with a missense variant in EZH2, and found discordant classification scores of 49% and 82%, respectively." (PMID 37022461, 2024). "We encountered this phenomenon again using the DNA methylation signature for Weaver syndrome, caused by pathogenic variants in EZH2, where variants in SUZ12 and EED had high classification scores (> 90%)." (PMID 37022461, 2024). "Here we developed and characterized what we believe to be a novel mouse model for the most commonly encountered pathogenic variant in Weaver syndrome, EZH2 p.R684C." (PMID 38015625, 2024). "Further, mutations in EZH2 are associated with Weaver syndrome which disrupts normal development during childhood and adolescence." (PMID 38670959, 2024). "In humans, mutations in EZH2 cause the Weaver syndrome and increased height, tall stature but also growth retardation and severe short stature." (PMID 38017417, 2023). "The rare Weaver syndrome linked to developmental cognitive deficits is caused by autosomal dominant mutations in any one of the three PRC2 core components EZH2, EED and SUZ12." (PMID 37842084, 2023). "Mutations in EZH2 (catalytic subunit of PRC2) have been associated with Weaver Syndrome, which is characterized by overgrowth and ID." (PMID 36845425, 2023). "In humans, mutations in the Ezh2 gene underlie Weaver Syndrome, a genetic disease associated with intellectual disability." (PMID 37326884, 2023). "Loss-of-function mutations in EZH2 and thus reduced H3K27me3 levels in humans have been shown to cause Weaver syndrome, causing overgrowth and macrocephaly, accelerated bone maturation, ASD, developmental delay and characteristic facial features." (PMID 33263776, 2021). "Mutations in the EZH2 gene in human are associated with Weaver syndrome, a rare genetic disease characterized by advanced osseous maturation, skeletal and neurological abnormalities." (PMID 33937229, 2021).